WIF1 (Wnt inhibitory factor 1)
Diseases named in the same sentence as WIF1 in open-access papers (continued):
Sharing a sentence is not in itself a finding about the gene and the disease.
cancer (continued). "WIF-1 methylation was also significantly higher in polypoid adenomas compared to carcinomas (WIF-1; 47% (8/17), p = 0.003)." (PMID 24350795, 2013). "Several reports have demonstrated that WIF-1 silencing due to hypermethylation results in Wnt signaling activation in a variety of cancer." (PMID 22448123, 2012). "Compared to other secreted Wnt antagonists, WIF1 has been consistently shown to inhibit the in vitro and in vivo growth of various cancer cells." (PMID 20573255, 2010). "The antiproliferation effect of WIF1 has been consistently reported in a wide variety of other cancer cell lines." (PMID 20573255, 2010). "Concordingly, in the mouse pluripotent embryogenic carcinoma cell line p19cl6, early and late Wif1 exposure enhances and attenuates differentiation, respectively." (PMID 21179454, 2010). "Despite, within the cohort of carcinomas being affected by methylation of either the DKK3 or WIF1 gene, a large fraction (45%) showed methylation in one gene only." (PMID 19570204, 2009). "In case of BC, LINC00592 was found to be located in the nucleus and could promote the growth and metastasis of cancer cells by enhancing the promoter methylation of WIF1 and decreasing WIF1 transcription." (PMID 39737397, 2024). "Moreover, WIF1 hypermethylation has been shown to be correlated with poor survival rate in some cancer patients, such as non-small-cell lung cancer, esophageal squamous cell carcinoma, and chondrosarcoma." (PMID 36619866, 2022). "WIF1 consists of a tumor suppressor gene that is epigenetically silenced in various cancers." (PMID 34997134, 2022). "For instance, theWIF1 (Wnt inhibitory factor 1) gene is down-regulated inmany cancers." (PMID 32745158, 2020). "When re-expressed,WIF1 can down-regulate the Wnt pathway and prevent cancer cellgrowth." (PMID 32745158, 2020). "Since WIF-1 plays a crucial role in controlling the expression of Wnt, therefore, it may be proposed that WIF-1 promoter-mediated changes in the expression of Wnt are important in the malignant tumor formation in gallbladders." (PMID 32140709, 2020). "WIF1 is a common target of epigenetic silencing in various human cancers." (PMID 29435185, 2018). "WIF1 is a frequent target for epigenetic silencing in various human cancers." (PMID 30591011, 2018). "Taken together, WIF1 methylation may be a common event in malignancies, and anti-methylation of WIF1 may improve patient survival and serve as a potential treatment in cancers, including in CS." (PMID 28484252, 2017). "However, limited data show the correlation between the cancer clinicopathological characteristics and the key molecules such as β-catenin and Wnt inhibitory factor 1 (WIF1)." (PMID 27843945, 2016). "WIF-1 inhibits Wnt signalling during development to help regulate Wnt expression in the paraxial mesoderm, and its promoter region is frequently methylated, and consequently downregulated in many cancers as detailed below." (PMID 27196929, 2016). "Most studies elevated WIF1 levels using the common DNA demethylating agent 5-azacytidine (5-Aza) and its derivative 5-aza-20-deoxycytidine (Decitabine), which have been tested in phase I and II trials for many forms of cancer." (PMID 25918249, 2015). "WIF1 was focally located in the lamina propria of WT cancers." (PMID 26461935, 2015). "Several groups have reported that restoring WIF-1 expression in cancer cells could inhibit cancer cell growth." (PMID 24755295, 2014). "We have focused on the Wnt antagonist gene WIF1 (Wnt inhibitor factor 1) because it has been reported that the epigenetic silencing of this gene induces an aberrant activation of the Wnt signaling pathway in many cancers." (PMID 24289328, 2013). "This may suggest that methylation of WIF-1 is less important in carcinomas or that silencing of these genes in carcinomas is achieved by other changes to the DNA." (PMID 24350795, 2013). "In addition, WIF1 restoration inhibited the in vivo growth of PCa cancer cells in a xenograft model." (PMID 20573255, 2010).
cancer (continued). "In parallel to the analyses in PE-explants, we also performed a series of signal transduction perturbations to investigate the role of Wif1 during first heart field cardiomyogenesis using the DMSO-induced cardiomyocyte differentiation in the mouse pluripotent embryogenic carcinoma cell line p19cl6." (PMID 21179454, 2010). "In addition, Wif1 function is required to prevent metastasis of cancer cells." (PMID 30574494, 2018). "Therefore, just as in some other carcinomas, WIF1 is a potent drug target in CC treatment." (PMID 27843945, 2016). "In addition, we have now identified specific genes (e.g, INHBA and WIF1), which while previously implicated in other cancer types, to our knowledge have not previously been implicated in carcinogenesis of OSCC." (PMID 20174472, 2010). "Accordingly, whilst WIF1 is frequently silenced in cancer, indolent CLL cells only rarely display WIF1 methylation and trisomy chr12 CLL is particularly associated with an anergic state that can be subverted to provoke cellular reactivation and apoptosis." (PMID 33447828, 2021). "Many of these RNAs have been extensively studied as cancer-related molecules, such as miR-181a, CCNE1, and WIF1." (PMID 33718161, 2021). "Our meta-analysis was unable to find any statistical significance between HBV-positive carcinoma tissues and HBV-negative carcinoma tissues for the methylation of the remaining seven genes, including RUNX3, p14, WIF1, CDH1, PRDM2, SOCS1 and MGMT." (PMID 31772678, 2019). "The meta-analysis of p14, WIF1, PRDM2, p15 and MGMT gene methylation was performed between HBV-positive carcinoma tissues and HBV-negative carcinoma tissues." (PMID 31772678, 2019). "Studies have shown that Wnt signaling pathway can be enhanced by repression of expression of these Wnt inhibitors such as WIF1, SFRP, DDK1 through both genetic and epigenetic alterations in human cancers." (PMID 30348169, 2018). "We also found a number of genes whose expression follows this pattern: high-grade cancers < low-grade cancers < normal tissue, such as ALDH1L1, WIF1, ACSL1, FOS, and ABLIM1 in at least four cancer types." (PMID 28427185, 2017). "Wnt inhibitory factor-1 (WIF1), one of the most important Wnt antagonists, is frequently down-regulated by promoter region hypermethylation in various types of cancer." (PMID 27110300, 2016). "Methylation level of DAPK1, SLIT2, WIF1 and RARB genes combined distinguished cancer from normal cervical tissues and had significantly higher specificity compared to HPV detection and age alone." (PMID 25826459, 2015). "Epigenetic regulation through histone modification or DNA methylation was also shown previously for other antagonists of Wnt signaling such as DACT3, sFRPs, WIF1 and DKK-1 in different cancer cells." (PMID 23658527, 2013). "We showed the potential of NPY, PENK, and WIF1 as combined epigenetic markers for CRC diagnosis, both in tissue and serum and tested their use as serum biomarkers in other cancers." (PMID 24289328, 2013). "Previous studies have shown that promoters of most WNT antagonistic genes (sFRP1, sFRP2, sFRP3, sFRP5, DKKs, and WIF1) are methylated or epigenetically silenced in RCC, which results in uninhibited WNT signaling during cancer initiation or progression." (PMID 23094073, 2012). "FZD8, WIF1 and SOX7 were identified by HTself as differentially expressed between cancer and luminal cells, and in whole tissue CP compared to NP." (PMID 20021671, 2009). "Moreover, a substantial reduction in DNA methylation results in the downregulated expression of inhibitors of Wnt, including Dickkopf-related protein 1 (DKK1), Wnt inhibitory factor 1 (WIF-1), and various frizzled-related proteins (SFRP1-5), in cancer cells." (PMID 40006021, 2025). "A logistic regression model, using 5 proteins (ITGB5, TGF-α, TLR3, WIF-1, and ERBB3) with highest AUC values, demonstrated good predictive performance for prognosis of CC patients undergoing immunotherapy and showed potential across different cancer types." (PMID 38835778, 2024).
cancer (continued). "The mechanism studies showed that overexpression of ALKBH5 could promote the transcription Wnt inhibitory factor 1 (WIF-1) via demethylation, thus inhibited Wnt pathway to sensitize cancer cells to chemotherapy." (PMID 36810281, 2023). "Many cancer-related molecules are included in this network, such as miR-181a, CCNE1, and WIF1." (PMID 33718161, 2021). "The epigenetic silencing of secreted Wnt pathway inhibitors related to cancer appears not restricted to Wif1 but holds true also for most other members such as Dkk1-3, Sost, Igfbp4 or sFRP1-5." (PMID 30574494, 2018). "The WIF1 gene was chosen for this study because of its known involvement in regulating tumorogenesis in various cancers, but had not yet been studied in CS." (PMID 28484252, 2017). "Moreover, there are numerous cancers with downregulation of extracellular Wnt inhibitors such as DKK1, sFRP and Wif1 that make the development of therapies targeting the Wnt ligand-receptor complex low hanging fruit." (PMID 27598201, 2016). "Obvious membranous staining of β-catenin and nuclear staining of WIF1 were observed in most cancer and noncancerous samples; however, both staining patterns were considered to be negatively expressed." (PMID 27843945, 2016). "Notably, augmentation of WIF1 expression was observed in ISL-treated mammary tissues, especially when the hyperplasia had developed to the carcinoma stage at the 12th week of age." (PMID 25918249, 2015). "Furthermore, promoter methylation or other epigenetic modification of WNT antagonistic genes such as extracellular antagoinsts (sFRPs, DKKs, and WIF1 genes) and cytosolic antagoinsts (DACTs, AXIN2, and APC genes) are also involved in the development of several cancers." (PMID 23094073, 2012). "However, WIF1 alone could not be considered as a unique marker for cancer detection, from effluents, although its discriminative value in tissues was very high." (PMID 24289328, 2013). "In the cancer cells as well as cancer cell lines (data not shown), there was increased expression of Wnt receptor FZD8; decreased expression of Wnt inhibitor WIF1, which functions to sequester Wnt molecules from receptor binding, and that of the transcription factor SOX7." (PMID 20021671, 2009).
infection (3 papers, 2014 to 2021). The state of being infected such as from the introduction of a foreign agent such as serum, vaccine, antigenic substance or organism. "The expression of Ciart, Per2, Cilp2, Tnmd, Col2a1, and Wif1 at each time point post-infection was significantly different from that observed in uninfected diaphragms (P < 0.0001)." (PMID 33648561, 2021). "Increased expression of miR-181a upon infection of miR-181a mimics, significantly suppressed luciferase expression derived from reporter constructs containing wild type WIF-1 3′-UTRs with inhibition rates 40% (p < 0.05) comparing to cells co-transfected with miR-SC." (PMID 24755295, 2014).
adenocarcinoma (2 papers, 2010 to 2017). A common cancer characterized by the presence of malignant glandular cells. "According to current findings, WIF1 promoter methylation was a frequent event as an epigenetic field manner and could be considered as a useful prognostic marker for adenocarcinoma patients." (PMID 29169318, 2017).
cardiovascular disease (2 papers, 2021 to 2024). "Interestingly, Wnt signaling is also critical for several pathological events leading to cardiovascular disease, e.g., Wnt Inhibitory Factor 1 (WIF1)." (PMID 38791593, 2024). "It is reported that the circulatory WIF‐1 and sFRP‐1 levels were significantly higher in non‐diabetic subjects who developed cardiovascular disease during the follow‐up period, suggesting the elevation in WIF‐1 may be a valuable predictor for future cardiovascular events." (PMID 34042263, 2021).
heart disease (2 papers, 2013 to 2023). "It is anticipated that our findings will contribute to expansion of our understanding of WIF1 biological function on heart development and possible modes of treatment of heart diseases." (PMID 23921644, 2013). "It is anticipated that our findings will contribute to expansion our understanding of WIF1 biological function on heart development and possible therapeutic strategy to control heart diseases." (PMID 23921644, 2013). "Furthermore, the inhibition of the Wnt signal induced by WIF1 could be reversed by LiCl, further suggesting that WIF1 acts as a negative regulator of Wnt pathway in the myocyte and is involved in the pathological development of heart diseases." (PMID 23921644, 2013).
hematological malignancies (1 paper, 2021). "One of the 5 studies of WIF1 in hematologic malignancies is related to MCL." (PMID 33477402, 2021). "Nonetheless, most of these studies of WIF1 methylation in hematological malignancies did not examine the biological significance of this defect." (PMID 33477402, 2021).
kidney disease (1 paper, 2022). "Here the authors report that podocyte claudin-5 regulates WNT signaling activity by modulating WIF1 expression, and its downregulation contributes to kidney disease progression in mice." (PMID 35332151, 2022). "Our experiments also provide proof of principle that CLDN5 and WIF1 might be developed into therapeutic modalities for the treatment of kidney diseases affecting millions of people worldwide." (PMID 35332151, 2022).
neurodegenerative disease (1 paper, 2024). A disorder of the central nervous system characterized by gradual and progressive loss of neural tissue and neurologic function. "Based on the existing literature, we hypothesized that WIF1 assumes a pivotal role in the regulation of neurodegenerative diseases within the context of DR, with particular emphasis on the impairment of photoreceptor cells and the function of neurons in the DR, which is affected by WIF1." (PMID 38448948, 2024).
WIF1 also shares sentences with these, for which no sentence is quoted: osteoarthritis (3 papers); Alzheimer’s dementia (2); brain cancer (2); intestinal tumors (2); metastatic colorectal cancer (2); neuroblastoma (2); ovarian carcinoma (2); acute promyelocytic leukemia (1); adrenocortical tumor (1); Alzheimer’s disease (1); angiosarcoma (1); bacterial infections (1); calcification (1); Cholecystitis (1); chronic lymphocytic leukemias (1); colonic adenoma (1); cutaneous melanoma (1); dementia (1); developmental dysplasia of the hip (1); fibrosarcoma (1); generalized epilepsy (1); head and neck squamous cell carcinoma (1); hepatopulmonary syndrome (1); Hereditary breast cancer (1); Hyperglycemia (1); hypertrophy (1); infectious disease (1); inflammation (1); intestinal cancer (1); intimal sarcoma (1).
A further 13 diseases each share a sentence with WIF1 in 1 paper.